CPLX4 (complexin 4)
Description:
Complexin that regulates SNARE protein complex-mediated synaptic vesicle fusion (By similarity). Required for the maintenance of synaptic ultrastructure in the adult retina (By similarity). Positively regulates synaptic transmission through synaptic vesicle availability and exocytosis of neurotransmitters at photoreceptor ribbon synapses in the retina (By similarity). Suppresses tonic photoreceptor activity and baseline 'noise' by suppression of Ca(2+) vesicle tonic release and the facilitation of evoked synchronous and asynchronous Ca(2+) vesicle release (By similarity).
Synonyms: CPX-IV; CPXIV
Tractability: Antibody: UniProt places it where antibodies can reach, with medium confidence; its Gene Ontology location is reachable by antibodies, with medium confidence.
Gene: Protein-coding gene on chromosome 18 (59,275,156 to 59,318,649, reverse strand). Ensembl gene ENSG00000166569.
Subcellular location: Synapse; Cell membrane
Gene Ontology:
Molecular function: protein binding; SNARE binding
Biological process: modulation of chemical synaptic transmission; regulation of synaptic vesicle fusion to presynaptic active zone membrane; synaptic vesicle exocytosis; neurotransmitter transport
Cellular component: SNARE complex; synapse; terminal bouton; plasma membrane
Genetic constraint (gnomAD): Loss-of-function variants: 14 observed, 12.3 expected, observed/expected ratio (o/e) 1.14, 90% interval 0.75 to 1.73. The upper end of that interval is the gene's LOEUF score, 1.73, which puts it in group 6 of 6, group 1 being the genes least tolerant of losing a copy. Missense variants: 153 observed, 162.34 expected, observed/expected ratio (o/e) 0.94, 90% interval 0.82 to 1.08. Synonymous variants: 45 observed, 48.69 expected, observed/expected ratio (o/e) 0.92, 90% interval 0.73 to 1.18.
Homologues: Orthologues: chimpanzee CPLX4 (100% identical), macaque CPLX4 (99% identical), dog CPLX4 (95% identical), pig CPLX4 (95% identical), guinea pig CPLX4 (94% identical), rabbit CPLX4 (94% identical), mouse Cplx4 (92% identical), rat Cplx4 (92% identical), tropical clawed frog cplx4 (77% identical), zebrafish cplx4a (74% identical), zebrafish cplx4b (52% identical), Drosophila melanogaster cpx (18% identical), and 2 more. Paralogues in human: CPLX3 (61% identical), CPLX2 (29% identical), CPLX1 (28% identical).
Diseases named in the same sentence as CPLX4 in open-access papers:
CPLX4 is named in the same sentence as 5 diseases in open-access papers, as found by Europe PMC text mining. Sharing a sentence is not in itself a finding about the gene and the disease. The quoted sentences say what the papers report.
breast carcinoma (1 paper, 2017). "Top HBF + BPA-dysregulated genes (ALDH1B1, ASTL, CA7, CPLX4, KCNV2, MAGEE2 and TUBA3E) are associated with poor overall survival in The Cancer Genomic Atlas (TCGA) human breast cancer cohort (n = 1082)." (PMID 28487351, 2017). "To gain clinical significance, using The Cancer Genomic Atlas (TCGA) breast cancer cohort, we dichotomized 1082 breast cancer subjects into two groups based on the expression of the seven genes (ALDH1B1, ASTL, CA7, CPLX4, KCNV2, MAGEE2 and TUBA3E)." (PMID 28487351, 2017). "We took advantage of the publicly available RNA-seq and survival data from TCGA and determined that seven differentially expressed genes (ALDH1B1, ASTL, CA7, CPLX4, KCNV2, MAGEE2 and TUBA3E) could be involved in breast cancer development, especially in Caucasian female patients with ER positivity." (PMID 28487351, 2017).
CPLX4 also shares sentences with these, for which no sentence is quoted: cancer (2 papers); epilepsy (1); neuroblastoma (1); tumor (1).